SNORD96B (small nucleolar RNA, C/D box 96B)
Synonyms: U96b
Gene: Small nucleolar RNA gene on chromosome X (110,224,985 to 110,225,063, reverse strand). Ensembl gene ENSG00000208883.
Gene Ontology:
Biological process: RNA processing
Cellular component: nucleolus
Homologues: Orthologues: chimpanzee SNORD96 (99% identical), rabbit SNORD96 (96% identical), pig SNORD96 (90% identical), dog SNORD96 (89% identical), mouse Snord96a (86% identical), rat Snord96a (84% identical). Paralogues in human: SNORD96A (92% identical).